NIM1K (NIM1 serine/threonine protein kinase)
Synonyms: NIM1; MGC42105
Tractability: Small molecule: a high-quality ligand is known; it belongs to a druggable protein family. PROTAC: a small molecule that binds it is known.
Target class: CAMK protein kinase NIM1 subfamily; Protein Kinase; Enzyme; CAMK protein kinase group; Kinase; CAMK protein kinase CAMK1 family
Gene: Protein-coding gene on chromosome 5 (43,192,071 to 43,280,862, forward strand). Ensembl gene ENSG00000177453.
Subcellular location (Human Protein Atlas): Cytosol
Gene Ontology:
Molecular function: ATP binding; magnesium ion binding; protein serine kinase activity; protein serine/threonine kinase activity; protein kinase activity
Biological process: intracellular signal transduction
Genetic constraint (gnomAD): Loss-of-function variants: 35 observed, 39.04 expected, observed/expected ratio (o/e) 0.9, 90% interval 0.68 to 1.19. The upper end of that interval is the gene's LOEUF score, 1.19, which puts it in group 5 of 6, group 1 being the genes least tolerant of losing a copy. Missense variants: 547 observed, 562.52 expected, observed/expected ratio (o/e) 0.97, 90% interval 0.91 to 1.04. Synonymous variants: 223 observed, 211.21 expected, observed/expected ratio (o/e) 1.06, 90% interval 0.95 to 1.18.
Homologues: Orthologues: chimpanzee NIM1K (99% identical), macaque NIM1K (99% identical), pig NIM1K (96% identical), guinea pig NIM1K (95% identical), dog NIM1K (94% identical), rabbit NIM1K (94% identical), mouse Nim1k (92% identical), rat Nim1k (92% identical), tropical clawed frog nim1k (76% identical), zebrafish nim1kb (54% identical), Drosophila melanogaster CG4629 (40% identical), Caenorhabditis elegans nimk-1 (40% identical). Paralogues in human: SIK3 (33% identical), SIK2 (32% identical), SIK1 (31% identical), PRKAA1 (29% identical), SNRK (29% identical), PRKAA2 (28% identical), NUAK2 (28% identical), NUAK1 (27% identical), MELK (27% identical), BRSK1 (26% identical), BRSK2 (26% identical), HUNK (25% identical), and 5 more.
Diseases named in the same sentence as NIM1K in open-access papers:
NIM1K is named in the same sentence as 5 diseases in open-access papers, as found by Europe PMC text mining. Sharing a sentence is not in itself a finding about the gene and the disease.
NIM1K shares sentences with these, for which no sentence is quoted: cancer (2 papers); atherosclerosis (1); bovine tuberculosis (1); infection (1); tumor (1).